MTOR (mechanistic target of rapamycin kinase)
Diseases named in the same sentence as MTOR in open-access papers (continued):
Sharing a sentence is not in itself a finding about the gene and the disease.
cancer (continued). "There have been several reports that local anesthetics regulate the PI3K/AKT/mTOR pathway to mediate cancer cell activities, including apoptosis and autophagy." (PMID 34696683, 2021). "As for quercetin, existing studies have indicated that quercetin is capable of inhibiting cell proliferation of cancer cell lines and regulating cancer metabolisms by modulating the PI3K-Akt-mTOR signaling and MAPK/ERK1/2 pathways." (PMID 33478536, 2021). "PTEN, a key molecule of P13K/Akt/mTOR signaling pathway, has been shown to be inhibited by miR-205, miR-200c, and miR-141 in several other cancers." (PMID 34692473, 2021). "To summarize, the accumulation of LD in cancer cells depends on the activation of SREBP and mTOR pathways, suggesting that both pathways are important in cancer development and progression." (PMID 35198567, 2021). "The results showed that p-mTOR was highly expressed in cancer tissues and positively correlated with HK2." (PMID 34345220, 2021). "The dysregulation of the mTOR pathway correlates to tumor development and progression, so mTOR has become a hot target for cancer therapy." (PMID 34205996, 2021). "The mammalian target of rapamycin (mTOR), which affects cancer progression and TAM polarization, contributes to the regulation of metastasis in many cancers." (PMID 35027915, 2021). "Taxifolin has also been reported to inhibit cancer cell growth in scar cancer cells by inhibiting the PI3K/Akt/mTOR pathway." (PMID 34235089, 2021). "Activation of the PI3K/Akt/mTOR signaling is essential for the development of various forms of cancers, especially in CRC, leaving this pathway as an important target for CRC treatment." (PMID 34796092, 2021). "Kyoto Encyclopedia of Genes and Genomes (KEGG) signal pathway analysis showed that the DEGs mainly regulated pathways in cancer, cell cycle, pyrimidine metabolism, and the mTOR signaling pathway." (PMID 33681194, 2021). "Despite the clear appeal of targeting PI3K/mTOR signalling for cancer therapeutics, there are challenges that prevent its full clinical impact." (PMID 34203293, 2021). "The dysregulation of the PI3K/AKT/mTOR signaling pathway is related to the occurrence and development of many human cancers." (PMID 34675984, 2021). "These researchers have also shown that alterations in the Akt/mTOR pathways in cancer cells can also induce both autophagy and apoptosis." (PMID 34944759, 2021). "L-g-glutamyl-p-nitroanilide is an inhibitor of SLC1A5 that leads to GLN starvation in cells and inhibits GLN-dependent mTOR activation, thus suppressing cancer progression." (PMID 34503536, 2021). "In cases of cancer, both mTOR and KRAS intersect the PKM2 nullcline in a stable state, where each of the three components has high activities." (PMID 33925206, 2021). "4E‐BP1 is a well‐validated downstream target whose phosphorylation is modulated based on the activation of the PI3K/AKT/mTOR signaling pathway, a pathway that is frequently activated in numerous cancers, including GC." (PMID 32460412, 2021). "In sum, mTOR pathway inhibitors are effective in cancer treatment, and their nature and application have garnered furthered research interest." (PMID 34361836, 2021). "The PI3K/AKT/mTOR signaling pathway plays a crucial role in controlling cancer cell-cycle and growth." (PMID 33916707, 2021). "We further discuss the therapeutic opportunities of combining mTOR inhibitors with immunotherapies in cancer treatment." (PMID 33802831, 2021). "The concept of identifying the mTOR pathway as the robust controller of the cellular metabolic program and defining cell-tissue specificity, including cancer cells, was recently proposed." (PMID 34832087, 2021). "Although several mTOR inhibitors have been developed because of the importance of Akt/mTOR pathway in cancer cell proliferation and chemoresistance, cancer cells frequently become mTOR inhibitor resistant." (PMID 33490663, 2021).
cancer (continued). "As a consequence, direct manipulation of immune cells metabolism by manipulating the PI3k/Akt/mTOR axis has the potential to provide a new avenue for cancer immunotherapy." (PMID 35250965, 2021). "The result showed these genes were enriched in the FoxO signaling pathway, Pathways in cancer, mTOR signaling pathway, PI3K-Akt signaling pathway, etc." (PMID 34290231, 2021). "AKT promotes Ras/Raf/ERK-1/2 and mTOR signaling cascades, which in turn enhances the proliferation and survival of cancer cells." (PMID 33996789, 2021). "The phosphatidylinositol 3-kinase (PI3K)/Akt/mammalian target of rapamycin (mTOR) cascade is recognized as an important sensor of nutrient/growth factor availability and a major pathway regulating autophagy in human cancers." (PMID 34178638, 2021). "According to HALLMARK collection defined by MSigDB, the genes in the high-risk group were mainly enriched in cancer stemness-related pathways, such as DNA repair and PI3K–Akt–mTOR signaling." (PMID 34568334, 2021). "Enhanced cellular signal transduction via mitogen-activated protein kinases (MAPK) and the mechanistic target of rapamycin (mTOR) facilitate the sustained proliferation of the cancer cells." (PMID 34208775, 2021). "Pedroza DA demonstrated that PGRMC1 plays a prominent role in regulating the growth of cancer cells by altering the PI3K/AKT/mTOR and EGFR signaling mechanisms in both ER-positive and TNBC cells." (PMID 34746100, 2021). "pS6 is an active marker for mTOR signalling which induces cancer growth and is downregulated in the presence of hypoxia." (PMID 34436447, 2021). "ETV has earlier been reported act as an essential component of a rapamycin-insensitive mTOR complex in cancer." (PMID 34926692, 2021). "Deregulation of the PI3K-Akt-mTOR pathway plays a critical role in the development and progression of many cancers." (PMID 35011901, 2021). "AMPK activation, in turn, inhibits the mammalian target of rapamycin (mTOR), thereby reducing both protein synthesis and proliferation of cancer cells." (PMID 33946426, 2021). "Numerous studies have examined the mammalian target of rapamycin (mTOR) signaling pathway as a target of cancer therapy." (PMID 34361836, 2021). "The study results revealed that GCMSCs contributed to dysfunctional NK cells involved at least partially in the inhibition of mTOR signalling, suggesting potential directions for NK cell-based cancer immunotherapy." (PMID 34306099, 2021). "Mitochondria-related apoptotic pathways, cell cycle arrest, and autophagy induced by the AKT/mTOR signaling pathway in cancer cells are all considered to be involved in this process, but the specific mechanism remains to be explored." (PMID 33996598, 2021). "Our results confirmed that BCAT1 enhances the mTOR-mediated autophagy via BACC Leu metabolism in cancer cells, which finally leads to a reduced cisplatin sensitivity." (PMID 33568627, 2021). "The mechanosensitive caveolin-1 activation-induced PI3K/Akt/mTOR signaling pathway promotes cancer motility, invadopodia formation and metastasis in vivo." (PMID 34540654, 2021). "Rapamycin‐insensitive companion of mTOR (Rictor) and Ras homolog enriched in brain (Rheb) have been recently reported as the direct targets of miR155 in cancer cells, and Rictor has been shown to play a critical role in mTORC2 induced Akt phosphorylation." (PMID 33210462, 2021). "PI-103 is a potent PI3K and mTOR inhibitor that exhibits antiproliferative properties in a panel of human cancer cell lines." (PMID 33986754, 2021). "The induction of the PI3K/AKT/mTOR pathway in cancer cells by fibroblasts can also promote the survival of cancer cells and impair their response to anti-HER2 kinase targeted therapies." (PMID 34298736, 2021).
cancer (continued). "To date, there are two different AATs (SLC1A5/ASCT2 and SLC7A5/LAT1) that have been reported to play important roles in the progression of different types of human cancers through mTOR activation." (PMID 34003553, 2021). "To date, more than a dozen different MTOR variants have been implicated in SKS, primarily localized within the focal adhesion targeting (FAT) and kinase domains of MTOR, which is where many cancer-associated MTOR variants are localized as well." (PMID 34197453, 2021). "Pathway in cancer, mTOR signaling pathway, MAPK signaling pathway, VEGF signaling pathway, and JAK-STAT signaling pathway were significantly enriched in the high-risk group (P < 0.05, FDR<0.25)." (PMID 33714257, 2021). "The Sal B-induced autophagy, which is mediated by the AKT/mTOR signaling pathway, can play a pro-apoptotic role in cancer cells." (PMID 34575981, 2021). "In such a context, a systemic mTOR inhibitor can be interesting in cancer-related treatments, but considering the key role Akt/mTORC1 signaling plays in muscle physiology and metabolism, this kind of drug can be detrimental for the muscles." (PMID 35008195, 2021). "RPTOR, along with TSC2, is a part of the mTOR signaling pathway known to affect many different types of cancer." (PMID 33466343, 2021). "Emerging evidence indicates that, at the cellular level, defects in p38 activation and PI3K/Akt/mTOR inhibition strongly facilitate pro-oncogenic functions for cancer survival." (PMID 34371964, 2021). "This underscores the importance of UBE2O’s regulation of the mTOR-HIF1a pathway for both the angiogenic signaling pathway, and the neovascularization necessary for cancer growth and metastasis." (PMID 34451875, 2021). "We demonstrate that patient-specific combination regimens which achieve mTOR blockade and tandem targeting of other tumor vulnerabilities not only lead to favourable outcomes in advanced refractory cancers but also had manageable toxicity profiles." (PMID 33935721, 2021). "mTOR-related hyperactivity correlated with metastases of other cancers was reported in a few lower case number studies (e.g., breast, lung, and renal carcinomas)." (PMID 35029792, 2021). "We found that mTOR was significantly overexpressed in the cancer tissues compared with that in the adjacent normal tissues." (PMID 33946531, 2021). "Among the reprogramming metabolic processes of cancer cells and immune cells, mTOR signaling seems to play a vital role in bridging metabolism and immunity." (PMID 34858835, 2021). "The role of mTOR inhibitors as potential anti-neoplastic agents has been investigated in a variety of canine cancers." (PMID 34895222, 2021). "The antitumor effect of systemic mTOR inhibition occurs mainly through inhibition of this pathway in cancer cells but is partly countered by the effect on TAMs." (PMID 33407885, 2021). "AKT and the phosphatidyl-3-kinase/AKT/mTOR pathway are hyperactivated in various cancers by upstream regulatory proteins." (PMID 34359969, 2021). "Licochalcone A (LA) and galangin have been proven to increase autophagy and apoptosis in cancer cells via the inhibition of PI3K/Akt/mTOR activation and downregulation of Bcl-2 expression." (PMID 33494431, 2021). "Multiple lines of evidence have suggested that PL treatment significantly modulated the NF-κB and PI3K/Akt/mTOR signaling pathway in different types of cancers, which provides a hint to explore more regarding the radiosensitizing potential of PL." (PMID 36046754, 2021). "Apart from vitamin A metabolism, the importance of ALDH and ADH were demonstrated in cancer cell proliferation, motility and metastasis, due to their specific role in affecting mTOR dependent signalling." (PMID 34178631, 2021). "Activated AMPK is able to exert anti-cancer cell activity by regulating its targets, including mammalian target of rapamycin (mTOR) complex 1 (mTORC1) inhibition, autophagy induction and degradation of various oncogenes." (PMID 33824293, 2021).
cancer (continued). "The PI3K–Akt–mTOR pathway is also a strong regulator of autophagy and is involved in the development and promotion of pathological disorders such as cancer." (PMID 34444753, 2021). "The activation of the Akt and mTOR-signaling pathways leads to enhanced cancer cell growth (increased protein synthesis), and proliferation (increase in cell number; Lamouille and Derynck, 2007, 2011)." (PMID 33996789, 2021). "Collectively, these data identify the interaction of H2S donors with the mTOR signaling pathway as a crucial event in promoting autophagy and apoptosis thence preventing cancer progression." (PMID 33390834, 2021). "Intercellular bridge structures between cancer cells have been reported to be regulated by mTOR signalling, while actin regulatory factors have been implicated in senescent cell TNTs." (PMID 34373767, 2021). "It was also shown that FTX/Nucb2 accelerated the metastasis of cancer through mediation in the phosphorylation of protein kinase B and mTOR." (PMID 34073612, 2021). "A study of endometrial cancer cells showed anti-cancer effects of genistein, concerning its capability to attenuate phosphorylation of mTOR pathway components." (PMID 34289845, 2021). "NFV has been shown to modulate PI3K/mTOR signaling in a variety of cancer cell types resulting in cell death; this is thought to be triggered by NFV-mediated induction of ER stress due to general inhibition of host proteasomes." (PMID 33668328, 2021). "The Akt/mTOR signaling pathway, which is widely acknowledged to have crucial functions in cells, is activated in many cancers and inhibits apoptosis, contributing to drug resistance in the clinic." (PMID 33845796, 2021). "With the significant advancement of understanding the functioning and regulation of mTOR, it is quite clear that these proteins are critically involved in the onset and progression of diabetes and cancer." (PMID 34535145, 2021). "Immunostaining for β-catenin and phosphor-S6 showed that niclosamide suppressed β-catenin expression while the metformin suppressed mTOR activity in cancer tissue." (PMID 34298652, 2021). "Mammalian target of rapamycin (mTOR) signaling, also modulated by PI3K-AKT, is on the most important biological pathways and it is implicated in various diseases ranging from cancer to neurodevelopmental pathologies." (PMID 35069108, 2021). "miR-99a can directly suppress the expression of its functional mRNA target mTOR in various cancer cell lines." (PMID 33657992, 2021). "PI3K/mTOR dual inhibitors have been assessed in several clinical trials as a treatment for various advanced cancers, but rarely GEP-NET." (PMID 34065268, 2021). "KEGG analyses further revealed the genes mainly participated in hypoxia-inducible factor (HIF)-1 signaling pathway, expression of cancer related microRNAs, IL-17 signaling pathway, central carbon metabolism in cancer cells and mTOR signaling pathway." (PMID 33767582, 2021). "The AKT and mTOR major regulatory signaling pathways are involved in the modulation of the proliferation, metabolism, and survival of cancer cells." (PMID 34093198, 2021). "For example, PI3K/Akt/mTOR pathway is a shared pathway in cancers and HF, drugs targeting the mTOR pathway, such as rapamycin, are novel potential drugs for HF which can reduce cardiac remodeling and HF." (PMID 34026868, 2021). "4F2hc-LAT1 shows an elevated expression level in certain types of cancer and thus provides the cancer cell with neutral and essential amino acids for regulation of the mammalian target of rapamycin (mTOR) signaling pathway and nutrition." (PMID 34449687, 2021). "In summary, we identified a key regulatory METTL14‐miR‐99a‐5p‐TRIB2 feedback circuit that epigenetically represses p21 through Akt/mTOR/S6K1/HDAC2 to promote cancer stemness and radioresistance in ESCC." (PMID 34586732, 2021). "Firstly, progranulin depletion not only downregulates Akt/mTOR signaling pathway but also upregulates production of TGF-β in cancer cells." (PMID 33490663, 2021).
cancer (continued). "In many cancer types, the mTOR signaling pathway is abnormally activated and is involved in tumor formation, the regulation of immune cell differentiation, and tumor metabolism." (PMID 34432955, 2021). "The mTOR signaling pathway is involved in the onset and progression of cancer, and the mTOR complex (mTORC1 and mTORC2) exerts its actions by regulating some important kinases, such as Akt." (PMID 33996604, 2021). "Trp depletion has been shown to inhibit mammalian target of rapamycin (mTOR) and protein kinase C in cancer cells and enhance autophagy and Treg development." (PMID 33401460, 2021). "We observed that these genes were involved in PI3K-AKT pathway, mTOR signaling pathways, microRNA in cancer pathway along with other pathways involved in cancer as per the analysis performed using DAVID25,56." (PMID 33990639, 2021). "Other studies have also shown that the PI3K/Akt/mTOR signaling pathway exerts an antiapoptotic effect and contributes to autophagic regulation in cancer cells." (PMID 33753729, 2021). "The compounds demonstrating good binding affinity scores, as revealed by MM-PBSA were confirmed as final hits and reported in this study as potential ATP-competitive mTOR kinase domain inhibitors for cancer therapeutic treatment." (PMID 33801030, 2021). "PLK1 is engaged in autophagy-mediating pathways involving mechanistic target of Rapamycin (mTOR) as a key kinase promoting (cancer) cell growth." (PMID 34065956, 2021). "Overall, we believe the potentiality of Hit1, Hit3 and Hit4 as alternatives and their scaffolds can be further explored for developing efficient ATP-binding site mTOR inhibitors for cancer therapeutics." (PMID 33801030, 2021). "Due to gene mutation, overexpression, and posttranslational modifications, aberrant mTOR activation is often detected in a significant proportion of NSCLC, which is heavily implicated in tumorigenesis and cancer progression." (PMID 34178653, 2021). "Autophagic mediators, including ATGs, PI3K, mTOR, and Beclin-1, can integrate into cancer cell signaling networks and ultimately determine cell survival or death." (PMID 34093198, 2021). "The PI3K/Akt/mTOR pathway has been demonstrated as one of the central regulators of glycolysis and cancer proliferation." (PMID 33791391, 2021). "We found that these marker genes were enriched in different biological processes and pathways in different cell subpopulations such as metabolic pathways, pathways in cancer, and mTOR signaling pathway." (PMID 34660776, 2021). "It inhibits the stimulation of AKT and mTOR in several cancer cells and reduces the phosphorylation of mTOR at the Ser2481 position." (PMID 34795581, 2021). "Increasing evidence has demonstrated that the mTOR complexes mTORC1 and mTORC2 participate in regulation of cell motility, invasion and cancer metastasis." (PMID 34178975, 2021). "AKT/rapamycin (mTOR) activation enables the continued growth and survival of tumor cells that rely on aerobic glycolysis, while the expression of NDFIP1 reduces the AKT/mTOR signaling pathway in cancer cells." (PMID 34676171, 2021). "It is of a great interest to test a powerful two-hit inhibition system in PH animal models given the fact that many dual PI3K/mTOR inhibitors emerged into clinical trials as anti-cancer agents." (PMID 33670032, 2021). "We found that most of the mTOR pathway-related genes had a high expression level in most cancers, except for a few genes such as CAB39L and PRKAA2, which had a lower expression in most cancers compared to normal tissues." (PMID 34194607, 2021). "In this study, we found that PI3K/AKT/mTOR inhibitors upregulated MIF expression and secretion in several PTEN-deficient cancer cells, and activated STAT3 activity through JAK1, eventually limiting the effects of these inhibitors." (PMID 33431808, 2021). "We therefore designed our study to target the mTOR dysregulation in cancer using marine-derived bioactive natural products employing a series of computational methods." (PMID 33801030, 2021).